SHC4 (SHC adaptor protein 4)
Description:
Activates both Ras-dependent and Ras-independent migratory pathways in melanomas. Contributes to the early phases of agrin-induced tyrosine phosphorylation of CHRNB1.
Synonyms: RaLP; SHCD
Tractability: Antibody: UniProt places it where antibodies can reach, with medium confidence; its Gene Ontology location is reachable by antibodies, with medium confidence.
Gene: Protein-coding gene on chromosome 15 (48,823,741 to 48,963,919, reverse strand). Ensembl gene ENSG00000185634.
Subcellular location: Postsynaptic cell membrane
Subcellular location (Human Protein Atlas): Cytosol
Gene Ontology:
Molecular function: protein binding; receptor tyrosine kinase binding; protein domain specific binding
Biological process: cell surface receptor protein tyrosine kinase signaling pathway; intracellular signal transduction
Cellular component: plasma membrane; postsynaptic membrane
Genetic constraint (gnomAD): Loss-of-function variants: 34 observed, 63.11 expected, observed/expected ratio (o/e) 0.54, 90% interval 0.41 to 0.72. The upper end of that interval is the gene's LOEUF score, 0.72, which puts it in group 2 of 6, group 1 being the genes least tolerant of losing a copy. Missense variants: 726 observed, 762.07 expected, observed/expected ratio (o/e) 0.95, 90% interval 0.9 to 1.01. Synonymous variants: 309 observed, 295.55 expected, observed/expected ratio (o/e) 1.05, 90% interval 0.95 to 1.15.
Homologues: Orthologues: chimpanzee SHC4 (99% identical), macaque SHC4 (97% identical), rabbit SHC4 (90% identical), pig SHC4 (90% identical), dog SHC4 (86% identical), mouse Shc4 (80% identical), rat Shc4 (79% identical), tropical clawed frog shc4 (52% identical), Drosophila melanogaster Shc (25% identical). Paralogues in human: SHC1 (45% identical), SHC3 (42% identical), CEP152 (17% identical).
Diseases named in the same sentence as SHC4 in open-access papers:
SHC4 is named in the same sentence as 23 diseases in open-access papers, as found by Europe PMC text mining. Sharing a sentence is not in itself a finding about the gene and the disease. The quoted sentences say what the papers report.
melanoma (15 papers, 2012 to 2025). A malignant, usually aggressive tumor composed of atypical, neoplastic melanocytes. "And SHC4 nuclear translocation protects melanoma cells from DNA damage caused by oxidative stress." (PMID 34414187, 2021). "A recent study in a melanoma mouse model found SHC4 reactivation greatly enhanced melanoma metastasis." (PMID 38426087, 2024). "In melanoma cell lines, ectopic SHC4 expression reduced cell adhesion, promoted amoeboid morphology of the tumor cells, and caused the activation of the MAPK pathway." (PMID 38426087, 2024). "SHC4 promotes tumor proliferation and metastasis in melanoma and hepatocellular carcinoma, whereas MEGF10 modulates the cellular aggressiveness of UVM." (PMID 36774490, 2023). "In 2007, SHC4 was discovered and positively identified in melanoma, and it was found to be critical in the development of metastatic melanoma in vivo." (PMID 36422523, 2022). "SHC4 promotes migration and invasion of melanoma cells through activation of Ras-dependent or Ras-independent pathways." (PMID 35033067, 2022). "The Src homology and collagen 4 (SHC4) is an important intracellular adaptor protein that has been shown to play a pro-cancer role in melanoma and glioma." (PMID 35033067, 2022). "In consistent with the studies on glioma and melanoma, our functional analysis showed that SHC4 enhanced cancer proliferation and invasion abilities at both the cellular and organismal levels." (PMID 35033067, 2022). "The considerably higher level of SHC4 expression in the perikaryon of melanoma cells is of note, and concurs with other studies showing restricted expression in melanomas, while only weakly expressed in normal melanocytes and benign nevi." (PMID 23638386, 2013). "There is evidence that SHC4 is highly expressed at the transition from radial growth phase to vertical growth phase and metastatic melanomas, contemporaneous with the acquisition of melanoma migratory competence and invasive potential." (PMID 23638386, 2013). "While SHC4 has been reported previously to be associated to melanoma, this is the first time CXCL13, COL11A1, and PTPRF have been associated with melanoma on experimental validation." (PMID 23638386, 2013). "COL11A1, CXCL13, PTPRF, and SHC4 were found to be over-expressed in two human melanoma cell lines (i.e., FM55 and FM94) compared to normal human epidermal melanocytes in vitro." (PMID 23638386, 2013). "SHC4 was first identified and confirmed in melanoma in 2007." (PMID 35033067, 2022). "High expression of SHC4 promoted the migration and invasion of melanoma cells and glioma cells." (PMID 35033067, 2022). "Overexpression of SHC4 in melanoma is a prerequisite for melanoma migration and invasion." (PMID 34414187, 2021). "The over-expression of COL11A1, CXCL13, PTPRF, and SHC4 in melanoma cells in vitro and in situ may reflect the observed over-expression of the associated genes in our microarray meta-analysis results." (PMID 23638386, 2013). "Third, we validated the expression of MAPK-associated members (COL11A1, CXCL13, PTPRF, SHC4) of the 12-gene biomarkers in a comparative analysis of normal melanocytes and melanoma cells in vitro and in primary versus metastatic melanoma biopsy tissue in situ." (PMID 23638386, 2013). "Finally SHC4 was found to be expressed in minor fraction of primary gp100-positive melanoma, but in most metastatic gp100-positive melanoma cells." (PMID 23638386, 2013). "Finally, SHC4 expression was membranous in normal melanocytes contrasting with some punctuate nuclear membrane expression in melanoma cells." (PMID 23638386, 2013). "The over-expression of COL11A1, CXCL13, PTPRF and SHC4 in our melanoma cell lines and primary and metastatic tissue, and their potential association with MAPK pathways suggests they could be specific biomarkers for melanoma and so potential therapeutic targets." (PMID 23638386, 2013). "SHC4 acts in cell signaling pathways, including the activation of MAPK/ERK, which is key in melanoma proliferation." (PMID 40647405, 2025).
melanoma (continued). "Normal melanocytes do not express SHC4, but its expression can be induced during the generation of malignant melanoma cells." (PMID 38426087, 2024). "However, six signature genes (i.e., IL8, SHC4, COL11A1, CHP2, PPP2R2C and WNT4) were not reported previously by microarray-based melanoma studies, although two (i.e. IL8 and SHC4) have been identified in independent wet-lab studies." (PMID 23638386, 2013).
glioma (6 papers, 2020 to 2023). A benign or malignant brain and spinal cord tumor that arises from glial cells (astrocytes, oligodendrocytes, ependymal cells). "Subsequent studies indicated that SHC4 is highly expressed in malignant gliomas and it can promote invasion in U87 glioma cells." (PMID 35033067, 2022). "SHC proteins are involving in the epidermal growth factor receptor (EGFR) internalization process and the increased expression level of SHC4 in glioma promoted the phosphorylation of EGFR specific sites." (PMID 35033067, 2022). "It was also demonstrated that the co-expression of Tie2 and ShcD/SHC4 in invasive glioma cells correlated with an increased expression of N-Cadherin, a classical marker of epithelial-to-mesenchymal transition (EMT) in cancer that supports mesenchymal and invasive phenotypes." (PMID 34830883, 2021).
breast carcinoma (5 papers, 2018 to 2025). "Our analysis pinpointed SHC4 and KCNK5 as essential genes within module 11, exhibiting significant correlations with the subtypes of breast cancer." (PMID 39834541, 2024). "SHC4 and PAK5 have both been studied in breast cancer, with the former being used as one of 12 gene signatures linking molecular mechanisms to disease prognosis, and the latter being associated with invasion, metastasis, and poor outcome in several cancers." (PMID 32620123, 2020). "Other downregulated genes, including breast cancer anti-estrogen resistance protein 1 (BCAR1, also known as p130Cas) and SHC adaptor proteins 3 and 4 (SHC3, SHC4), are key players in the regulation of cell migration by acting as scaffolds for tyrosine kinase-related signaling." (PMID 30086712, 2018).
hepatocellular carcinoma (5 papers, 2022 to 2024). A malignant tumor that arises from hepatocytes. "They further noted that a high expression of SHC4 is associated with clinicopathological features and poor prognoses in patients with hepatocellular carcinoma." (PMID 36290460, 2022). "It was reported that SHC4 was involved in the progression of hepatocellular cancer and prostate cancer." (PMID 36816023, 2023). "However, the biological function and detailed mechanisms of SHC4 in hepatocellular carcinoma progression are unclear." (PMID 35033067, 2022).
metastatic melanoma (5 papers, 2013 to 2022). A melanoma that has spread from its primary site to another anatomic site. "Ernesta Fagiani etc. found that SHC4 expression is essential for the growth of metastatic melanoma in vivo." (PMID 35033067, 2022).
prostate carcinoma (3 papers, 2022 to 2025). A carcinoma that arises from epithelial cells of the prostate gland. "PFDN4, when combined with SHC4 and CHORDC1, regulates extracellular vesicle secretion in prostate cancer." (PMID 36438659, 2022).
astrocytomas (2 papers, 2022). "The authors used a quantitative PCR (qPCR) analysis of biopsy cores representing Grade I–IV astrocytomas to demonstrate the significantly higher expression of SHC4 in tumor tissue compared to benign tissue." (PMID 36290460, 2022).
alcoholism (1 paper, 2022). "Interestingly, the GO term “alcoholism” was enriched in genes associated with the “CGI-free intergenic UMR” category, including Shc3, Shc4, Araf, Fosb, Hdac11, Adcy5, Creb3l2, Gnai2, Grin2d, and Ppp1r1b." (PMID 35205351, 2022).
bipolar disorder (1 paper, 2023). A disorder of the brain that causes unusual shifts in mood, energy, activity levels and the ability to carry out day-to-day tasks. "Finally, regarding the DMR, SNPs within the region comprising the associated genes SHC4 and EID1 have been related with psychiatric disorders such as major depressive disorder, bipolar disorder, mood and psychotic disorders, obsessive compulsive disorder, and schizophrenia." (PMID 36385171, 2023).
microcephaly (1 paper, 2025). A congenital or acquired developmental disorder in which the circumference of the head is smaller than normal for the person's age and sex. "SHC4 is not linked to microcephaly, growth retardation, or Seckel syndrome in OMIM, ClinVar, or the literature, and has no known role in MCPH–SCKS-related neuronal proliferation pathways." (PMID 41306914, 2025). "The proband’s severe microcephaly/growth restriction exactly matches CEP152-related MCPH–SCKS, with no SHC4-associated features." (PMID 41306914, 2025).
Primary microcephaly (1 paper, 2022). Head circumference below 2 standard deviations below the mean for age and gender at birth. "Mutations in CEP152 have been associated with primary microcephaly; SHC4 is mainly expressed in the testes and brain; and EID1 may play a crucial role in lipid accumulation and proliferation of neural stem cells." (PMID 35440892, 2022).
tumor (10 papers, 2012 to 2025). "Further research on cell lines showed that knockdown and inhibition of STAT3 attenuates the proliferation, migration and invasion of tumor cells caused by overexpression of SHC4." (PMID 35033067, 2022). "Given the complex regulation of gene expression, several key upregulated genes were found, including GATA4, SALL3, IL33, SOX10, and SCG3/SHC4, while the downregulation of keratin genes suggests a loss of epithelial differentiation, contributing to aggressive tumor behavior." (PMID 40647405, 2025). "When we integrated several of these genes into a multivariate LASSO regression model to define poor tumour outcome in the BX‐Neu+ mouse cohort, four genes were identified that were associated with poor survival in BX‐Neu+ mice: Oip5, Higd1a, Shc4 and Scrg1." (PMID 38344872, 2024). "The effects of SHC4 repression or overexpression on migration, invasion, and tumor growth were detected by colony formation assay, wound healing, transwell assays, and xenograft assay." (PMID 35033067, 2022). "SHC4 was overexpressed in HCC compared to adjacent normal liver tissues and increased SHC4 expression was associated with high AFP level, incomplete tumor encapsulation, poor tumor differentiation and poor prognosis." (PMID 35033067, 2022). "Chi-squared analysis indicated that high SHC4 expression was notably associated with gender (P = 0.003), AFP level (P < 0.01), tumor encapsulation (P = 0.002), and tumor differentiation (P = 0.023)." (PMID 35033067, 2022). "Consistent with the function of STAT3 in vitro, inhibition of STAT3 by Stattic largely eliminated the enhancement in tumor growth induced by SHC4 overexpression." (PMID 35033067, 2022). "Experiments on mice had also been conducted to verify that SHC4 promoted tumor growth, and Stattic could reverse this effect." (PMID 35033067, 2022). "IHC staining confirmed the SHC4 overexpressed efficiency in xenograft tumor tissues." (PMID 35033067, 2022). "Tumor xenograft model assay confirmed the oncogenic role of SHC4 in tumorigenicity in nude mice." (PMID 35033067, 2022). "To assess the therapeutic potential and examine the role of STAT3 in SHC4-induced tumorigenesis, we performed another subcutaneous xenograft model, in which nude mice were peritoneally treated with Stattic for 4 weeks after subcutaneous tumor reached 3–5 mm in diameter." (PMID 35033067, 2022). "In our study, qRT-PCR analysis showed SHC4 (15.85-fold), SOS2 (2.78-fold), CCDC6 (6.18-fold), and KRAS (5.92-fold) were up-regulated significantly in tumor tissues." (PMID 23285163, 2012). "Additionally, we found that female patients and patients with high AST and AFP, poor tumor differentiation, advanced TNM stage, incomplete tumor encapsulation appeared to exhibit high SHC4 expression." (PMID 35033067, 2022).
cancer (9 papers, 2013 to 2023). A tumor composed of atypical neoplastic, often pleomorphic cells that invade other tissues. "SHC4 works as an oncogene and causes carcinoma cells to proliferate and become malignant." (PMID 36290460, 2022). "However, the mechanism of SHC4 action in cancer cells, especially in HCC, largely remains unknown." (PMID 35033067, 2022).
psychiatric disorder (1 paper, 2023). A disorder characterized by behavioral and/or psychological abnormalities, often accompanied by physical symptoms. "This DMR included 6 CpGs mapped to the SHC4 gene that has previously been implicated in multiple types of psychiatric disorders in adulthood." (PMID 36385171, 2023).
SHC4 also shares sentences with these, for which no sentence is quoted: bladder cancer (1 paper); Cirrhosis (1); glioblastoma (1); major depressive disorder (1); malignant glioma (1); meningioma (1); obsessive-compulsive disorder (1); schizophrenia (1); Seckel syndrome (1).